IGF1R (insulin like growth factor 1 receptor)
Diseases named in the same sentence as IGF1R in open-access papers (continued):
Sharing a sentence is not in itself a finding about the gene and the disease.
neuroblastoma (46 papers, 2009 to 2025). Neuroblastoma (NB) is the most common solid, extracranial childhood tumor. "In this study, we showed that the MEK inhibitor trametinib and the IGF1R inhibitor ganitumab synergistically inhibited RAS-mutated neuroblastoma cell proliferation and induced apoptosis in cell culture models." (PMID 39001383, 2024). "In summary, these results suggest that the addition of an IGF1R inhibitor to a MEK inhibitor provided modest therapeutic enhancement in heterotopic RAS-mutated neuroblastoma models." (PMID 39001383, 2024). "In this study, we tested the efficacy of a combination of the MEK inhibitor trametinib and the IGF1R inhibitor ganitumab in RAS-mutated neuroblastoma models." (PMID 39001383, 2024). "As such, IGF-1R targeted monoclonal antibodies are currently being trialed in the clinical setting for patients with high-risk neuroblastoma." (PMID 24349301, 2013). "IGF-1R signaling has been previously implicated in neuroblastoma biology, as well as in other human cancers." (PMID 24349301, 2013). "By contrast, R1507 was ineffective in the chemoresistant neuroblastoma cells, which was most likely caused by reduced expression of the IGF-1R." (PMID 23056595, 2012). "In addition, we showed that trametinib and ganitumab inhibited proliferation in RAS-mutated neuroblastoma cells, even cells with a low expression of IGF1R." (PMID 39001383, 2024). "Indeed, IGF1R inhibition has been associated with decreased neuroblastoma cell growth and shown potent anti-tumor effects." (PMID 33889818, 2021). "The binding of IGF1 to IGF1R has been implicated in regulating neuroblastoma metastasis to bone, highlighting the multifaceted role of the IGF1/IGF2‐IGF1R axis in disease progression and dissemination." (PMID 40679030, 2025). "Our study was not designed to determine the individual effects of MEK inhibition and IGF1R inhibition on neuroblastoma tumor dissemination." (PMID 39001383, 2024). "Monoclonal antibodies specific for the IGF1R ligands, as well as inhibitors of PI3 kinase and mTOR, which are activated by signaling through IGF1R, are also effective in neuroblastoma models." (PMID 39001383, 2024). "Future studies will define the effects of MEK or IGF1R inhibition on the invasive and metastatic capacity of RAS- and NF1-mutated neuroblastoma models." (PMID 39001383, 2024). "Nonetheless, a recent study demonstrated that many neuroblastoma (NB) cell lines exhibit IGF-1R activity, and inhibiting IGF-1R leads to decreased cell proliferation in ALK-driven NB cells." (PMID 38397899, 2024). "In this study, we assembled a panel of RAS- and NF1-altered neuroblastoma cell lines with variable IGF1R expression to evaluate the efficacy of the combination of a MEK inhibitor (trametinib) and an IGF1R inhibitor (ganitumab) in neuroblastoma." (PMID 39001383, 2024). "Because both MEK and IGF1R inhibitors are effective in RAS-driven neuroblastoma, we sought to evaluate the combination of trametinib and ganitumab in this malignancy." (PMID 39001383, 2024). "In contrast, all the RAS/MAPK pathway-altered neuroblastoma lines expressed the insulin receptor, which is highly homologous to IGF1R, to a similar extent as MCF7 cells, except CHP-212." (PMID 39001383, 2024). "Decreasing the expression of IGF1R or AKT2 in neuroblastoma cells decreases proliferation, migration, and invasion, validating the IGF1R/PI3 kinase/AKT pathway as a potential therapeutic target in neuroblastoma." (PMID 39001383, 2024). "In prior studies, single agent MEK or IGF1R inhibitors induced transient responses as single agents in neuroblastoma models." (PMID 39001383, 2024). "Here, we investigated IGF1R in ALK-driven neuroblastoma, with the aim of understanding its contribution and exploring its potential for targeted therapy." (PMID 37686528, 2023). "Mechanistically, in ALK-mutated neuroblastoma cells, both ALK and IGF1R contribute significantly to the activation of the downstream PI3K-AKT and RAS-MAPK signaling pathways." (PMID 37686528, 2023).
neuroblastoma (continued). "We were extremely curious about this compound’s effect on the α-syn accumulation in primary dopaminergic neurons since in the literature, both insulin and IGF-1R are reported to reduce α-syn toxicity in the neuroblastoma cell lines." (PMID 35454152, 2022). "To this end, we used the EWS-FLI1 positive SK-N-MC cell line, which originally was thought to be of neuroblastoma origin, but later was recategorized as originating from an Ewing family sarcoma and which is highly IGF1R-positive." (PMID 35220407, 2022). "On the other hand, a number of studies have characterized the pro-oncogenic activities of IGF1R in neuroblastoma cell lines and tumor models." (PMID 34716856, 2022). "In contrast, Dp44mT and DpC consistently downregulated PDGFRβ and IGF-1R in both neuroblastoma cell lines." (PMID 36160437, 2022). "INSR expression shows a correlation with degree of apoptosis and dedifferentiation in human neuroblastomas, and is co-expressed with insulin-like growth factor 1 receptor." (PMID 30786925, 2019). "IGF-1R inhibitors have also been shown to enhance TMZ-sensitivity in neuroblastoma and medulloblastoma." (PMID 26497996, 2015). "First experiments had been carried out with an anti-GD2-ab neuroblastoma model system and were also performed with anti IGF1 R modified HSPC/Chol/DSPE-mPEG liposomes in a GEP-NET model." (PMID 26497207, 2015). "ALK, FGFR1, RET, PDGFRA, DDR2, EGFR, and IGF1R were enriched in endosomes from two or more neuroblastoma cell lines, but there were profound differences among cell lines." (PMID 25884760, 2015). "EGFR and IGF-1R activation has been shown to increase cell proliferation, inhibit apoptosis, induce resistance to chemotherapy and increase Mycn protein levels in neuroblastoma." (PMID 24759734, 2014). "Additional preclinical studies showed both single agent anti-IGF-1R activity and additive effects when combined with more standard chemotherapies in some neuroblastoma cell lines." (PMID 23383402, 2013). "Phosphopeptides from several RTK’s that are known for their oncogenic roles in other human tumors were identified in this neuroblastoma cell line, including IGF-1R/IR, FGFR1, FGFR2, Ret, and DDR2." (PMID 24349301, 2013). "Our analysis therefore supports the importance of IGF-1R/IR signaling in neuroblastoma tumor biology." (PMID 24349301, 2013). "Targeting receptor tyrosine kinases such as the IGF-1R is a promising approach to develop novel anti-cancer therapies in embryonal tumors, such as neuroblastoma and sarcoma." (PMID 23056595, 2012). "In the present report we have evaluated the anti-proliferative activity of the humanized anti-IGF-1R antibody R1507 in the embryonal tumors neuroblastoma and medulloblastoma in vitro." (PMID 23056595, 2012). "In the present study, the impact of the humanized anti-IGF-1R antibody R1507 was evaluated on cell proliferation in vitro in the panels of neuroblastoma and medulloblastoma cell lines." (PMID 23056595, 2012). "The IGF1R inhibitor A-928605 was also able to significantly retard the growth in a model of neuroblastoma." (PMID 19732452, 2009). "In addition, signaling through the IGF1R/PI3 kinase/AKT/mTOR pathway facilitates neuroblastoma metastasis to bone and induces resistance to cytotoxic chemotherapy, retinoic acid, and ALK inhibitors." (PMID 39001383, 2024). "Importantly, small-molecule and monoclonal antibody inhibitors of IGF1R potently decrease neuroblastoma cell viability and delay tumor growth in xenograft models of neuroblastoma." (PMID 39001383, 2024). "Using ALK-driven neuroblastoma cell lines, we show that ALK-mutated cells are more sensitive to IGF1R inhibition than ALK-amplified cells, and a synergistic effect is obtained when combining ALK and IGF1R inhibitors." (PMID 37686528, 2023).
neuroblastoma (continued). "Earlier work in cell culture demonstrated that MAPK phosphorylates ERα at S118 following IGF-1 treatment, and recent work from our laboratory in a neuroblastoma cell line supports the role of neuroestrogens in activating the MAPK pathway in conjunction with IGF-1R." (PMID 36261268, 2022). "Our previous results have shown that IGF-1R was overexpressed on neuroblastoma cells." (PMID 35399718, 2022). "This points to a central role of IGF1R in regulation of Akt signaling in the neuroblastoma cells." (PMID 33889818, 2021). "Taken together, our work reveals high levels of IGF-1R/IR and Ret phosphopeptides, with associated high abundance of phosphopeptides from downstream mediators of the PI3K/Akt/mTor and Raf/MEK/ERK pathways in MYCN-amplified neuroblastoma." (PMID 24349301, 2013). "Neuroblastoma cell lines are sensitive to the IGF-1R inhibitor BMS-536924." (PMID 23383402, 2013). "In addition, we identified a number of phosphopeptides from protein tyrosine kinases that are activators of these pathways and potential oncogenic drivers of neuroblastoma cell growth, including IGF-1R/IR and Ret." (PMID 24349301, 2013). "By treating neuroblastoma and medulloblastoma cells with R1507, a specific humanized monoclonal antibody against the IGF-1R, we could observe cell line-specific responses and in some cases a strong decrease in cell proliferation." (PMID 23056595, 2012). "Previous studies have shown that the genetic knockdown of IGF1R expression using shRNA decreased the transwell invasion of neuroblastoma cells such as IMR32 and SH-SY5Y; however, the effect of IGF1R inhibition on RAS- or NF1-altered neuroblastoma cell invasion is unknown." (PMID 39001383, 2024). "Among the several cellular functions induced by this RTK in neuroblastoma cells, a major one is cell differentiation, suggesting that under specific in vivo contexts, IGF1R suppressive activities might dominate over pro-oncogenic activities observed in cell culture." (PMID 34716856, 2022). "The increased IGF1R levels upon Cbl knockdown could potentially be coupled with increased neuroblastoma cell viability or proliferation, as we do observe a slightly higher dependency on IGF1R for cell survival of Cbl/Cbl-b-depleted SH-SY5Y cells treated with IGF1R inhibitor." (PMID 33889818, 2021). "Thus, there could be a rationale for further investigations into the possibilities of combining IGF1R inhibition with differentiation therapy through modulation of Cbl protein signaling networks for the treatment of neuroblastoma." (PMID 33889818, 2021). "Additionally, IGF-1R is a major determinant of the metastatic potential of neuroblastoma." (PMID 23383402, 2013). "In contrast to previous reports using the IGF1R monoclonal antibody EM164, the anti-proliferative effects of ganitumab as a single agent on neuroblastoma cells were modest." (PMID 39001383, 2024). "The increased activity of the IGF1R/PI3 kinase/AKT/mTOR pathway induces proliferation, prevents apoptosis, increases motility, induces differentiation, and drives MYCN expression in neuroblastoma cells." (PMID 39001383, 2024). "The insulin-like growth factor 1 receptor (IGF1R) is a receptor tyrosine kinase (RTK) widely expressed in many cancers, including the pediatric cancer neuroblastoma." (PMID 37686528, 2023). "In neuroblastoma, it has been reported that MAML3 over-expression increased IGF2 transcription independently from Notch, and this mediated IGF1R activation and AKT signaling, resulting in an increased cell proliferation." (PMID 35163581, 2022). "GALNT2 overexpression altered the Tn antigen expression by neuroblastoma (NB) cells and suppressed malignant proliferation of NB cells, as a result of decreased dimerization of IGF-1R (Insulin-like growth factor receptor), a critical glycosylation target for GalNAcT2." (PMID 27322213, 2016).
neuroblastoma (continued). "Our results demonstrate high levels of phosphopeptides from IGF-1R/IR, as well as its major substrates, IRS-2 and Shc, in MYCN-amplified neuroblastoma cells." (PMID 24349301, 2013). "Another ginsenoside Rg1 attenuated cytotoxic effects of neurotoxin 6-OHDA on human neuroblastoma cells through IGF-1R receptor signaling, indicating that ginsenoside-mediated IGF-1R signaling is cell-type specific depending on agents used." (PMID 23889969, 2013). "Our analysis highlights the importance of RET, IGF-1R/IR and FGFR1 as RTKs in neuroblastoma and suggests a methodology that can be used to identify potential novel biological therapeutic targets." (PMID 24349301, 2013). "We have previously shown that the IGF-1R tyrosine kinase inhibitor NVP-AEW541 enhances the effects of cisplatin on cell proliferation and apoptosis in neuroblastoma cell lines." (PMID 23056595, 2012). "In the present report, we have evaluated the anti-proliferative potential of the humanized anti-IGF-1R antibody R1507 and of PIK75, a class IA PI3K inhibitor, in medulloblastoma and neuroblastoma cell lines." (PMID 23056595, 2012). "The IGF1R pathway is aberrantly activated by autocrine and paracrine signaling loops in neuroblastoma tumors through the release of IGF1 and IGF2, ligands for IGF1R, from the neuroblastoma and stromal cells within the tumor." (PMID 39001383, 2024). "Isolated targeting of IGF-1R/IR, Ret, PI3K, MEK, and mTor has been trialed in neuroblastoma, with or without traditional chemotherapy." (PMID 24349301, 2013).
lung adenocarcinoma (43 papers, 2009 to 2024). A carcinoma that arises from the lung and is characterized by the presence of malignant glandular epithelial cells. "In the present study, we have investigated the involvement of IGF1R in acquired high-dose erlotinib resistance in the EGFR-mutated lung adenocarcinoma cell line HCC827." (PMID 28418902, 2017). "In the present study, we investigate the role of IGF1R in acquired resistance to erlotinib in the EGFR exon19del mutated lung adenocarcinoma cell line HCC827." (PMID 28418902, 2017). "GA and GA + AA genotypes of IGF1R rs2229765 had significant association with EGFR mutation in female lung adenocarcinoma patients (OR = 0.35, 95% CI = 0.15–0.82 and OR = 0.39, 95% CI = 0.17–0.87, respectively)." (PMID 27213344, 2016). "The results indicated that GA + AA genotypes of IGF1R rs2229765 were significantly associated with EGFR mutation in female lung adenocarcinoma patients (odds ratio (OR) = 0.39, 95% confidence interval (CI) = 0.17–0.87)." (PMID 27213344, 2016). "GA + AA genotype of IGF1R rs7166348 was shown to be significantly associated with the clinical N stage in lung adenocarcinoma (OR = 1.66, 95% CI = 1.07–2.95; p = 0.024)." (PMID 27213344, 2016). "GA + AA genotype of IGF1R rs7166348 shows significant association with the clinical stage in lung adenocarcinoma (OR = 1.66, 95% CI = 1.07–2.59)." (PMID 27213344, 2016). "The data show that IGF-1 reduces the activity of PKM2 in ARPE-19 cells, consistent with our previous observations in a human lung adenocarcinoma cell line, suggesting that activation of IGF1R signaling is associated with a decreased activity of the pyruvate kinase enzyme across multiple cell types." (PMID 39769402, 2024). "Our results showed that IGF1R genetic variants are related to EGFR mutation in female lung adenocarcinoma patients and may be a predictive factor for tumor lymph node metastasis in Taiwanese patients with NSCLC." (PMID 27213344, 2016). "Furthermore, GA + AA genotype of IGF1R rs7166348 was also shown to be significantly associated with clinical N stage in wild-type lung adenocarcinoma patients (OR = 2.75, 95% CI = 1.20–6.31)." (PMID 27213344, 2016). "TROP2 gene, that codes a cell surface glycoprotein is downregulated in lung adenocarcinoma patients, and its silencing through DNA methylation leads to a decreased suppression of IGF-1R signaling." (PMID 39638246, 2024). "In lung adenocarcinoma cells, IGF-1R-mediated EMT is probably dependent on the STAT3 and STAT5 pathways." (PMID 39638246, 2024). "FURIN is also strongly associated with carboxypeptidase D (CPD), recently reported to be required for pro-IGF1R maturation in lung adenocarcinoma." (PMID 35768873, 2022). "The growth factor amphiregulin participates in the nuclear accumulation of IGF1R in lung adenocarcinoma by allowing the binding of IGF1R to importin-β1." (PMID 33918477, 2021). "For example, CPD is necessary for the formation of the active insulin-like growth factor 1 receptor (IGF1R); deletion of the CPD gene inhibited signaling through IGF1R and reduced the three-dimensional growth of a lung adenocarcinoma cell line." (PMID 33217972, 2020). "The overexpression of GAS5 varied inversely with the expression of EGFR pathway and IGF-1R proteins in lung adenocarcinoma tissues." (PMID 30853980, 2019). "NOTCH1 activates AKT-1 via PTEN repression and induction of the insulin-like growth factor 1 receptor (IGF-1R) in lung adenocarcinoma during hypoxia." (PMID 30087852, 2018). "Taken together, these observations suggest that SOCS2 is involved in the regulation of IGF1R-mediated EMT of lung adenocarcinoma cells, which is probably dependent on the STAT3 and STAT5 pathway." (PMID 29559623, 2018). "To validate the activation of IGF1R/NF-κB p65 signaling in gefitinib-resistant mouse lung adenocarcinoma, we used genetically engineered mice harboring a doxycycline-inducible human EGFR exon 19 deletion transgene (hEGFR Del19)." (PMID 29190911, 2017).